SUMO1P1 (SUMO1 pseudogene 1)
Description:
Ubiquitin-like protein that can be covalently attached to proteins as a monomer or as a lysine-linked polymer. Regulates the life cycle of promyelocytic leukemia nuclear bodies (PML-NBs). PolySUMO1P1/SUMO5 conjugation on 'Lys-160' of PML facilitates recruitment of PML-NB components, which enlarges PML-NB. SUMO1P1/SUMO5 also increases polySUMO2/3 conjugation of PML, resulting in RNF4-mediated disruption of PML-NBs.
Synonyms: PIC1L; formerly UBL2; UBL6
Gene: Processed pseudogene on chromosome 20 (53,875,252 to 53,875,557, reverse strand). Ensembl gene ENSG00000241721.
Subcellular location: Nucleus
Diseases named in the same sentence as SUMO1P1 in open-access papers:
SUMO1P1 is named in the same sentence as 6 diseases in open-access papers, as found by Europe PMC text mining. Sharing a sentence is not in itself a finding about the gene and the disease. The quoted sentences say what the papers report.
type 2 diabetes (2 papers, 2018 to 2025). "Gene association studies have so far identified 16 candidate loci involved in PCOS, including genes involved in gonadotropin action (LHCGR and FSHR), metabolism and sexual development (ESR1), insulin signaling and type 2 diabetes (INSR, THADA, HMGA2) or cell proliferation (YAP1 and SUMO1P1)." (PMID 40551954, 2025).
breast tumors (1 paper, 2024). "Furthermore, the SUMO1P1 desert region is more accessible in highly proliferative compared with lowly proliferative breast tumors." (PMID 38625038, 2024). "One such region is near the SUMO1P1 pseudogene and shows a dramatic decrease in accessibility in MG132-treated cells, along with high accessibility in non-basal breast tumors (right)." (PMID 38625038, 2024). "Summary figures for SE regions near VMP1/MIR21 (Chr 17), SUMO1P1 (Chr 20), and PVT1 (Chr 8) are shown as representative examples from cluster A, B, and D, respectively, showing higher accessibility in non-basal compared with basal breast tumor samples." (PMID 38625038, 2024).
SUMO1P1 also shares sentences with these, for which no sentence is quoted: promyelocytic leukemia (3 papers); leukemia (1); type 2 diabetes mellitus (1); viral infection (1).